ITGB8 (integrin subunit beta 8)
Diseases named in the same sentence as ITGB8 in open-access papers (continued):
Sharing a sentence is not in itself a finding about the gene and the disease.
tumor (52 papers, 2011 to 2026). "ITGB8 plays a role in self-renewal and survival of neural progenitor cells and is associated with glioma tumor grade." (PMID 35267434, 2022). "miR-93* has been demonstrated to promote tumor growth and angiogenesis via targeting of integrin-B8 (encoded by ITGB8)." (PMID 29176973, 2017). "However, using scRNA-seq analysis, we identified high expression of the β8-encoding gene ITGB8 in tumor-infiltrating macrophages." (PMID 39743547, 2025). "Notably, ITGB8 + macrophages exhibited elevated levels of pro-tumorigenic markers associated with M2-like tumor-associated macrophages, including FN1, IL1β, CCL4L2, and CCL3L1." (PMID 39743547, 2025). "We found ITGA3 significantly associated with primary therapy outcome (p < 0.0001), ITGA6 significantly associated with OS status (p = 0.026), ITGB4 significantly associated with cancer status (p = 0.042) and tumor residual (p = 0.024), ITGB8 significantly associated with chemotherapy (p = 0.020)." (PMID 32765584, 2020). "Several high-scoring proteins, including ITGB8, LGR5, FZD7, HLA-E, ANGPTL2, and BST2 emerged as candidates potentially affected by protonation-linked perturbations in acidic tumor microenvironments." (PMID 42036641, 2026). "The identification of transcription factors such as BPTF, SOX4, and KLF5 in ITGB8-high cells further implicates these factors in regulating tumor–stroma interactions and mediating the aggressive phenotype associated with a high MTSR." (PMID 41602481, 2026). "Our in vitro findings further support the role of ITGB8 in promoting an immunosuppressive tumor environment through the release of active TGF-β1." (PMID 41463213, 2025). "A unique cluster of tumor cells in D‐TGCT is identified that regulated differentiation of CD34+ fibroblasts into MMP3+ fibroblasts or APOE+ fibroblasts via COL6A3 − (ITGAV + ITGB8) interaction." (PMID 40126353, 2025). "In the future, we will evaluate the usefulness of immunohistochemistry of ITGB8 tumor tissues in predicting BCG treatment efficacy." (PMID 41463213, 2025). "After removing tumor cells, ITGB8 was predominantly expressed in myeloid cells, particularly macrophages." (PMID 39743547, 2025). "In our study, scRNA-seq revealed that ITGB8 is highly expressed in epithelial cells or epithelial-derived tumor cells, as well as in tumor-infiltrating macrophages." (PMID 39743547, 2025). "To confirm this observation, we analyzed ITGB8 expression in tumor-infiltrating Tregs across various tumor tissues." (PMID 39743547, 2025). "The abundance of ITGB8 in tumor cells was significantly higher than in immune cells, prompting a re-analysis of tumor-infiltrating immune cells with the exclusion of tumor cells." (PMID 39743547, 2025). "In the recurrence group, a significantly greater area of the entire tumor was positive for ITGB8 (p = 0.03), TGF-β1 (p = 0.05), and TGF-β1 LAP (p = 0.05) compared with the non-recurrence group." (PMID 41463213, 2025). "For example, ITGB8 was found to play a tumor-suppressive role in KIRC, as patients with higher ITGB8 expression displayed longer OS time and lower tumor stages." (PMID 39436262, 2024). "RT-PCR analysis of xenograft tumor lysates revealed that the expression levels of E-cad, Slug, ITGB8, ITGB1, PCNA, and BAX showed a similar pattern to those observed in vitro, and Western blot results also confirmed these findings." (PMID 39459033, 2024). "Within the tumor, the highest Itgb8 expression levels were observed in CD4+ T cells, particularly in CD4+CD25+ Tregs compared to conventional CD4+CD25− T cells." (PMID 36382146, 2022). "Shown to be required for tumorigenicity, ITGB8 regulates tumor invasion, growth, and progression by promoting TGFβ receptor signaling and mitotic checkpoint progression." (PMID 35267434, 2022). "Among the integrin β‐subunits, ITGB1, ITGB2, ITGB4, ITGB5, ITGB6, ITGB7, and ITGB8 were highly expressed in tumour tissues compared with normal tissues." (PMID 34709754, 2021).
tumor (continued). "The expression of ITGA4, ITGA8, ITGB2, ITGB7 and ITGB8 was correlated with the infiltration of all types immune cell and tumor purity in the SKCM TIME." (PMID 34660316, 2021). "In contrast, ITGB8 (10/10) protein levels were increased in adjacent tissues compared with tumour tissues." (PMID 34709754, 2021). "Log scale analyses showed that ITGAV and ITGB8 transcripts were more strongly expressed in four out of 15 tumour samples compared to autologous proximal healthy lung tissues." (PMID 34471106, 2021). "Downregulation of circ_0037655 also promoted the miR-1229-3p level and restrained ITGB8 protein expression in tumor tissues." (PMID 34017919, 2021). "The results showed that there was a significant correlation between tumor stage and mRNA expression of ITGB8 in LUSC." (PMID 31875161, 2019). "The results revealed that the expression levels of ITGA11, ITGB4 and ITGB8 were all significantly upregulated in tumor tissues compared with normal tissues." (PMID 31875161, 2019). "We also performed a data-mining analysis to investigate the differences in the expression levels of ITGA11, ITGB4 and ITGB8 between tumor and normal tissues in NSCLC using GEO datasets." (PMID 31875161, 2019). "Notably, genes implicated in oncogenic signaling and tumor progression, including GNB4, EGF, MYB, IL6R, ANGPT4, and ITGB8, were consistently downregulated in both BxPC3 and SW1990 cells following PCDH1 silencing." (PMID 41602375, 2026). "In cases of recurrence, ITGB8-positive BCa cells that survive due to immune escape secrete immunosuppressive cytokines, suggesting that they could have escaped the anti-tumor immunity induced by BCG treatment and recur intravesically." (PMID 41463213, 2025). "In addition, immunohistochemistry of tumor tissue showed higher expression of ITGB8, TGF-β1, and TGF-β1 LAP, which indicates latent TGF-β1 activation in recurrent cancer tissues compared with non-recurrent cancer tissues after BCG treatment." (PMID 41463213, 2025). "To identify transcription factors (TFs) mediating AKR1B10’s regulation of integrin expression, we analyzed proteins that bind integrin gene promoters in HCT116 cells and the ITGB8 promoter across various tumor cell lines using the chromatin immunoprecipitation (ChIP)–Atlas database." (PMID 40845116, 2025). "Additionally, ITGB8 exerts regulatory effects on tumor cell proliferation and invasion and tumor growth by modulating the adhesion plaque signaling pathways." (PMID 39356055, 2024). "Latent TGFβ1 is expressed in diverse tumor cells and can be activated by binding to ITGB8." (PMID 35676251, 2022). "Itgb8 RNA was much lower in tumor cells and other lymphocytic and myeloid cell types." (PMID 36382146, 2022). "The expression of circ_0055625, which is associated with pathological TNM staging and promoted tumor growth and metastasis, was found to be significantly upregulated in CRC tissues through the activation of integrin subunit beta 8 (ITGB8) via the sponging of miR-106b." (PMID 34829818, 2021). "First, we confirmed that human T cells expressed ITGβ8 in the TME by analyzing single-cell mRNAseq, and reported that ITGB8 expression was prevalent in the Foxp3pos compartment of the TME of various tumor types, with 65-70% of Itgβ8pos T cells being Foxp3pos T cells." (PMID 34711823, 2021). "Of note, given that ITGB8 expression was reported to be increased on activated human Tregs18, we also removed the gene signature of activated Tregs in the ITGB8 Treg signature and obtained similar survival prognostics as with the ITGB8 Treg total gene signature for all the tumor types we analyzed." (PMID 34711823, 2021). "ITGB8 inhibition impaired self-renewal ability, stemness, migration, and tumor formation capacity." (PMID 32565741, 2020).
tumor (continued). "Furthermore, we found that there was a strong correlation between ITGB8 expression level and tumor stage in LUSC." (PMID 31875161, 2019). "We next ascertained whether miR-148a-mediated down-regulation of PAI-1, VAV2, ITGA5, and ITGB8 expression resulted in the inhibition of malignant progression of tumor cells." (PMID 21703006, 2011). "However, the effects of ITGB8 on tumor neovascularization are much more complex." (PMID 35676251, 2022). "In short, we identified an exclusive tumor cell subpopulation MP3 in D‐TGCT and confirmed the role of these tumor cells in regulating differentiation of CD34+ Fbs toward APOE+ Fbs and MMP3+ Fbs through COL6A3 − (ITGAV + ITGB8) interaction." (PMID 40126353, 2025). "The results showed that ITGA1, ITGB1, ITGB8 and SDC1 were highly expressed in tumor cells when compared with control group." (PMID 38526745, 2024). "In the present study, we provided clinical, in vitro and animal evidences demonstrating that GSCs-derived ITGB8 exhibits anti-angiogenic effect on brain microvascular endothelial cells, and contributes to VM formation and EMT in GBM to support tumor invasion." (PMID 35676251, 2022). "Among these, ITGB8, RELN, and SPP1 were the top tumor-promoting candidates significantly downregulated (FDR < 0.05) by YBX1 knockdown in the ECM-receptor interaction pathway." (PMID 31481087, 2019). "In our integrated analysis, we discovered a unique subpopulation of tumor cells (MP3 cluster) in D‐TGCT that could regulate differentiation of CD34+ Fbs into MMP3+ Fbs and APOE+ Fbs through the COL6A3 − (ITGAV + ITGB8) ligand–receptor pair." (PMID 40126353, 2025). "Additionally, tumor adhesion and metastasis-promoting molecules, including ITGB4 and ITGB8, whereas ITGA1 and ITGA2 were downregulated in ST6GAL1-knockdown cells." (PMID 39937175, 2025). "The analysis suggested that TECs might promote tumor growth and progression through the interaction of COL4A1/COL4A2 with their partner receptors (ITGAV + ITGB8 and ITGA3 + ITGB1) on epithelial cells." (PMID 39093451, 2024). "However, the mechanism by which PIK3R3, ITGB8, TrkB, and CACNA1D induce cell autophagy and inhibit tumor growth remains to be elucidated." (PMID 36386893, 2022). "Based on the in vitro transcriptome analysis and validation of “cytokine-cytokine receptor interaction,” “PI3K-Akt signaling pathway” and “MAPK signaling pathway,” we measured the relative protein expression of TGFB2, INHBB, PIK3R3, ITGB8, NTRK, and CACNA1D in tumor tissue." (PMID 36386893, 2022). "Next, in order to assess whether Itgβ8 expression by Tregs confers their abilities to control the anti-tumor immune responses by providing a bioactive source of TGF-β, we first selectively ablated Itgb8 in Tregs, using Foxp3-Cre Itgb8fl/fl mice (Foxp3ΔItgβ8)." (PMID 34711823, 2021). "Furthermore, we investigated the correlation between tumor stage and the expression levels of ITGA11, ITGB4 and ITGB8." (PMID 31875161, 2019). "Notably, ITGB8, DICER1, INPP5A, PIK3R1, and TIMP2 are key tumor suppressors that were among up-regulated CRGs following CBX2 knockdown." (PMID 26877821, 2016). "Moreover, we identified novel substrates like LGALS3BP, ITGB8, CD36, and ECE1, which may contribute to malignant tumor progression." (PMID 39937175, 2025). "Although ITGB8 expression was associated with recurrence in our study, the small sample size precluded reliable multivariable modeling to establish whether ITGB8 has independent predictive value beyond conventional clinical factors such as stage, grade, CIS, multiplicity, and tumor size." (PMID 41463213, 2025). "Notably, β8 seemed not to affect the stiffness of tumor cells, as evidenced by either ITGB8 knockout or overexpression." (PMID 37614365, 2023). "Since ITGB8 caused opposite prognosis in patients with GBM, we speculated that endothelial-based angiogenesis mainly accounts for the outcome and tumor progression in GBM-bearing mice when no therapeutic intervention was received." (PMID 35676251, 2022).
tumor (continued). "Because the study cohort consisted of only 13 patients, multivariable analysis to assess whether ITGB8 expression had independent predictive value beyond standard clinical risk factors (stage, grade, CIS status, multiplicity, and tumor size) was not statistically feasible." (PMID 41463213, 2025). "Using ITGB8 promoter-GFP-expressing MCF-7 cells, we also observed that the expression of β8 was only upregulated in M-stiff cells but not in H-stiff tumor cells cultured in soft fibrin gels." (PMID 37614365, 2023).
cancer (29 papers, 2007 to 2026). A tumor composed of atypical neoplastic, often pleomorphic cells that invade other tissues. "KEGG enrichment analysis further showed that the WNT signaling pathway was the most markedly enriched pathway in the ITGB8-high group, alongside several other cancer-related pathways." (PMID 41602481, 2026). "Mechanistically, we established that CAFs-derived MFAP2 interacts with integrin β8 (ITGB8) on cancer cell surfaces, activating the integrin-FAK-ERK1/2 signaling cascade to drive CRC progression." (PMID 41617683, 2026). "Our results revealed that cancer stem-like cells derived from primary GBM displayed abundant ITGB8 expression." (PMID 35676251, 2022). "For example, miR-199a-3p downregulated ITGB8 expression to impede cancer progression, contributing to the improvement of cisplatin sensitivity." (PMID 34250246, 2021). "ITGB8 is a member of the integrin β-chain subfamily, which was abnormally increased in several types of cancer." (PMID 34250246, 2021). "Eight ITGs were CNV-driven in human cancers, and ITGB8 showed a CNV-driven upregulation in four cancer types." (PMID 34222028, 2021). "ITGB8, a member of the integrin β-chain subfamily, was reported to be highly expressed in several cancers and was found to be closely related to the chemoresistance in cancer." (PMID 34250246, 2021). "Numerous studies have suggested that ITGA11, ITGB4 and ITGB8 are involved in migration, epithelial-mesenchymal transition, invasion, and metastasis in different cancers." (PMID 31875161, 2019). "Among these genes, we have several growth factor receptors and integrins, including ITGB8 whose relevance in cancer remains to be characterized." (PMID 18211678, 2008). "In addition, the PI3K/AKT pathway-related genes including FXYD3, SMAD7, and ITGB8, are involved in stem cell-like properties in various cancer types, which are transcriptionally regulated by SETD541–47." (PMID 37963940, 2023). "Furthermore, numerous studies have shown that ITGB8 and EIL4E proteins are associated with cancer migration, invasion and metastasis and autophagy." (PMID 36386893, 2022). "The aberrant expression of ITGA11, ITGB4, and ITGB8 have been reported in many cancers." (PMID 31875161, 2019). "The sequential genes upregulated during the progression from cancer stage 1 to 4 are CALB1, TPD52L1 and ITGB8." (PMID 39149248, 2024). "Further CellChat analysis revealed that the signaling pathways between cancer cells and identified CAFs (NRG1-ERBB2/4 and FN1-CD44/ITGAV/ITGA3/ITGB6/ITGB8/ITGB1) were specifically enriched in CAde and CSCC, respectively." (PMID 37879219, 2023). "ITGB8 is a member of the integrin β-chain subfamily to form integrin complexes, thus mediating interactions between cell-cell and -ECM in cancers." (PMID 32175330, 2020). "We selected potential miR-148a cancer-related target genes, namely ITGA11, ITGB8, VAV2, ROCK1 and WASL, which are known to be involved in integrin pathway-promoting cell migration, motility, actin polymerization, and cytoskeleton remodeling." (PMID 25277193, 2014). "In carcinoma samples the expression of both genes is elevated, with EPHB4 being significantly up-regulated in comparison to benign tissue samples, but expression of both ITGB8 and EPHB4 is much lower than in PIN tissues." (PMID 25886373, 2015). "It has been reported that ITGB8 could mediate the activation of latent TGF- β, which subsequently derives the epithelial-to-mesenchymal (EMT) transition of some cancers and contributes to cancer cell migration and growth." (PMID 31875161, 2019). "Notably, our data provide evidence for MUC4/Y upregulates ITGB8 downstream of the actin cytoskeleton pathway (ITGB8-FAK-Cas/CrkII/DOCK180 complex-RAC- IRSp53- WAVE2-Arp2/3-F-Actin/PFN complex) to affect actin dynamics and cancer cell motility." (PMID 25367394, 2014).